IL10 (interleukin 10)
Diseases named in the same sentence as IL10 in open-access papers (continued):
Sharing a sentence is not in itself a finding about the gene and the disease.
asthma (continued). "In addition, asthma conditions have been linked to increased levels of inflammatory cytokines such as IL-4, IL-5, IL-17, IL-13, and TNF-α in addition to decreased IFN-γ and IL-10." (PMID 39295946, 2024). "IL-10 expression may have a great significance for asthma and is low in asthma." (PMID 39282108, 2023). "Additionally, polysaccharide A derived from Bacteroides fragilis has a well-documented ability to suppress multiple rodent models of inflammatory diseases in an IL-10–dependent manner, including asthma, experimental autoimmune encephalomyelitis, and abscess formation." (PMID 37314833, 2023). "The overall effect of IL-10 is the downregulation of cytokine production and pro-inflammatory genes in their targets T cells, B cells, NK cells, and granulocytes, which in turn may downregulate airway inflammatory responses as seen in asthma." (PMID 37947634, 2023). "Since IL-4, IL-5, IL-10, IL-17, and IL-33 would not be measured in peripheral blood samples, we think it is not feasible to use these cytokines in clinical practice or in the research of the underlying mechanisms of the asthma phenotypes." (PMID 36326393, 2022). "It was also reported that AUR could treat Th2 cells diseases such as asthma by inhibiting cell proliferation, decreasing the levels of cytokines (IL-4, IL-10, and IFN-γ) and NF-κB, and reducing nitric oxide (NO) production in phytohemagglutinin (PHA) stimulation." (PMID 35873643, 2022). "Consequently, we hypothesized that determining IL-10 responses in steroid-resistant and -sensitive asthmatics proves that a former infection induces alterations in a different manner in asthma phenotypes." (PMID 32054098, 2020). "Finally, IL-10 has pleiotropic functions in critical features of asthma (ameliorate airway inflammation, induce AHR and remodeling), coupled with different regulators of its expression and actions, which raise the controversy, and make the interpretation account for additional challenges." (PMID 32024540, 2020). "In previous reports, it was shown that IL-10, with its immunoregulatory capacity, may participate in regulation of the eosinophil count and serum IgE levels without a direct effect on asthma susceptibility." (PMID 31336954, 2019). "However, in agreement with the findings of the present study, the concentration of IL-10 in BAL fluid of human asthmatic patients is lower than in healthy controls, and an inverse association between asthma severity and IL-10 concentration has been established." (PMID 31694631, 2019). "In early studies we demonstrated that 1,25(OH)2D3 restored the impaired steroid-induced IL-10 response in steroid refractory asthma patients both in vitro and in vivo, and clinical studies now provide evidence for modest steroid-sparing effects on vitamin D in asthma patients." (PMID 30690074, 2019). "However, it has recently also been reported that mice lacking ARNT/ HIF-1α signalling in myeloid cells have increased allergic response in both a house dust mite model and an OVA murine asthma model, which may be driven by decreased IL-10 production." (PMID 31800592, 2019). "However, lack of significant correlation between IL-10 and IL-17A in mild asthma patients suggests different function of these cytokines during initiation of asthma which environment is considered as a causal role." (PMID 30915130, 2018). "However, the suppressive capacity of LPS-primed BM-DC in vitro did not translate into suppression of allergic airway disease in vivo since intranasal administration of these LPS + IL-10-primed BM-DCs into mice was unable to prevent allergic airway inflammation in a mouse model of OVA-induced asthma." (PMID 29616018, 2018). "The block of IL-10 related signal may significantly augment airway neutrophilia in asthma." (PMID 29861841, 2018).
asthma (continued). "The results of Spearman’s analysis showed that serum IL-10 was positively correlated with IL-4, and sE-selectin was positively correlated with sICAM-1 and sVCAM-1, suggesting that IL-10 and sE-selectin accelerate the development of allergic rhinitis and asthma." (PMID 30344593, 2018). "However, there are studies in mice and man suggesting that IL-10 may contribute to asthma pathogenesis." (PMID 25430775, 2015). "It was suggested that IL-10, when already present during a virus infection in a disease characterized by a type 2 cytokine milieu such as allergic asthma, by suppressing antiviral immune responses, could play an important role in RV-induced asthma." (PMID 25430775, 2015). "However, a large dataset, focused on a healthy cohort, allowed us to identify statistically significant differences in the expression of CCL20, CCL2 and IL-10, all of which are important during rhinovirus infection and virally induced asthma exacerbations, after exposure with HRV16 and HRV1A." (PMID 24736642, 2014). "IL-13 and IL-10 responses were not independently associated with asthma, eczema or atopy." (PMID 24875149, 2014). "IL-10-producing B cells may mediate cooperative effects with regulatory T cells, while FasL+ B cells have been shown to have antigen-specific killer effects on T helper cells in models of asthma and autoimmunity." (PMID 23429492, 2013). "Therefore, the clinical results indicate that the MDSCs immune cell and IL-10 and IL-12 cytokines are significantly regulated in asthmatic children and might play important roles during the onset and development of asthma." (PMID 23717481, 2013). "In a murine model of ovalbumin-induced asthma, inhibition of lung inflammatory process, by S. mansoni eggs or by the S. mansoni antigens, Sm22.6, PIII, and rSm29 were associated with an increase in the number of CD4+CD25+Foxp3+ T cells and high levels of IL-10 production." (PMID 23209879, 2012). "Dysregulation in IL-10 expression, sometimes caused by single-nucleotide polymorphisms (SNPs) in the IL10 promoter have been associated to autoimmune and infectious diseases, such as SLE, asthma, chronic viral diseases, rheumatoid arthritis as well as transplantation complications and cancer." (PMID 22685464, 2012). "Indeed, IL-10-producing mature DCs expressing high levels of B7-1 and B7-2 have been shown to induce the development of Tr1 cells that can inhibit inflammation in a model of asthma." (PMID 21716731, 2011). "However, in individuals with asthma and wheezing, the effects of IL-10 still remain unclear, indicating the complex effects of regulatory cytokines in relation to the pathogenesis of asthma." (PMID 23724228, 2011). "No SNP in the IL10 gene was significantly associated with asthma or atopy in the BHS." (PMID 19852851, 2009). "In addition, IL-10 production is decreased in peripheral blood mononuclear cells of patients with mild asthma and is further attenuated in severe persistent asthma compared to mild asthma." (PMID 18315837, 2008). "Also, anti-inflammatory cytokines such as IL-10, IL-12, IL-18, IL-21, IL-23, IL-27 and interferons may have a therapeutic potential in asthma." (PMID 18315837, 2008). "However, recent studies have shown that not only Th1-related cytokines, but also other anti-inflammatory cytokines, including TGF-β and IL-10, can downregulate Th2 responses and might also play an important role in regulating pulmonary inflammation and asthma." (PMID 16677403, 2006). "However, the role of IL-10 in regulating Th2-mediated diseases such as asthma is controversial." (PMID 16677403, 2006). "Oral administration of L. reuteri ATCC 23272 also resulted in immunoregulatory effects, with elevated IL-10 levels and reduced levels of IL-5, IL-13, MCP-1, and TNF-α in OVA-induced asthma mice." (PMID 39820222, 2025). "The relevance between the FEO‐03 network and asthma on the KEGG Pathways database presented EPX, IL4, IL5, IL13, CD40LG, TNF, and IL10 according to p value." (PMID 40777200, 2025).
asthma (continued). "We examined the correlations of serum IL-36 levels with serum IL-6, IL-8, IL-10, IL-13, IL-17, IFN-γ, and TNF levels, except for IL-4 and IL-5 levels, which were only rarely observed in our asthma patients." (PMID 40115968, 2025). "In our asthma model, we observed an increase in CD19+IL-10+ B cells along with both types of macrophages during asthma attacks, with a positive correlation between the percentage of CD19+IL-10+ B cells and macrophages." (PMID 40342727, 2025). "PTGS2, IL10, CTSB, JAK2, and MTOR were significantly downregulated in alveolar lavage fluid with increasing asthma severity, while MMP9, GSK3B, BCL2, EGFR, and CCND1 were upregulated." (PMID 40160461, 2025). "A study revealed that in an ovalbumin (OVA)-induced asthma model, cDC1-induced CD4+ T cells secreted significantly more IL-4, IL-6, and IL-10, whereas cDC1-induced higher frequencies of IFN-γ and IL-17A production by CD4+ T cells." (PMID 39530090, 2024). "The findings indicate that I3C significantly (p < 0.05) downregulated IL-10 and IL-17 levels compared to OVA treatment, indicating that I3C helps regulate the balanced pathway of Th17/Treg cells to alleviate asthma’s inflammatory symptoms." (PMID 38731707, 2024). "A previous study suggested a significant decrease in the number of IL-10-positive cells in patients with COPD and asthma." (PMID 38774212, 2024). "A decrease in IL-10+ Breg frequency and/or function has also been seen in patients with Rheumatoid Arthritis (RA), Systemic lupus erythematosus (SLE), and asthma." (PMID 39346706, 2024). "Several studies have noted a decrease in various cytokines such as IFN-γ and IL-10, along with higher levels of both IL-6 and IL-8, suggesting an overactivation of pro-inflammatory mechanisms in patients with hemoglobinopathies, which could trigger inflammatory conditions such as asthma." (PMID 38892971, 2024). "IL-10 is an anti-inflammatory cytokine, and its production is increased in several diseases, including pulmonary illnesses such as ALI and asthma in an attempt to reestablish homeostasis." (PMID 39861071, 2024). "The production of IL-10 was significantly elevated in the probiotic-only, SLIT 132, and combined 132 groups compared to the asthma group (p < 0.001)." (PMID 39770422, 2024). "Asthma inflammation was characterized by elevated serum IL-6, increased lung cytokines (TNF-α, IL-6, IL-10), and higher fungal abundance confirmed by polymerase chain reaction (PCR)." (PMID 39484217, 2024). "Other studies also showed that IL-10 secretion from the gastric mucosa was increased in children with HP infection, and NAP inhibited Th2 responses by activating FOXP3+Tregs in an asthma model." (PMID 39564136, 2024). "In the present study, there was an increase in the inflammatory markers involved, such as IL-1β, IL-4, IL-5, IL-6, IL-10, IL-13, IL-17, IFN-γ, and TNF-α, in the experimental model of asthma-COPD overlap." (PMID 37511021, 2023). "Ourteam also reported an increase in the levels of IL-17A cytokines and a decrease in the levels of IL-10 in BALF, and the Th17/Treg imbalance is an important mechanism in asthma development." (PMID 37485534, 2023). "Remarkably, in asthmatic children undergoing AIT, a combination treatment with VD3 further enhanced the increase in Tregs, IL-10, and TGF-β and reduced nasal symptoms and asthma." (PMID 37371795, 2023). "The treatment also reversed the OVA-induced increase of IL-4, TNF-α, and decrease in IL-10 and IFN-γ in these mice, indicating its anti-inflammatory role in obese asthma." (PMID 37893170, 2023). "Long-term follow-up studies with larger participant cohorts are necessary to observe changes in vitamin D, IL-4, IL-10, and CD23+ levels and the development of asthma to explain and prove the effect of these variables on the incidence of bronchial asthma." (PMID 37760982, 2023). "IL-4 and IL-17 are critical inflammatory factors in asthma, and IFN-γ and IL-10 are essential anti-inflammatory factors." (PMID 36636604, 2023).
asthma (continued). "IL-10 is reported to block the conversion from naïve CD4+ T cells to Th2, alleviating the symptoms of asthma." (PMID 35812246, 2022). "Consistently, we detected IL-4, IL-5, IL-13, IL-25, IL-10, IL-33, and TSLP in induced sputum of asthma and proved a positive correlation between BIRC3 and these cytokines." (PMID 35287655, 2022). "In order to explore the relationship between the expression of IL1-RL1 in sputum supernatant of patients with asthma and type 2 inflammation, we analyzed the correlation between IL1-RL1 and Th2 inflammatory factors, such as IL-4, IL-5, IL-10 and IL-13." (PMID 35578178, 2022). "Related to this, interstitial macrophages have immunoregulatory properties by secreting IL-10 upon LPS and CPG-DNA stimulation in models of asthma." (PMID 35100872, 2022). "Allergic events (asthma or cow’s milk allergy) and atopic dermatitis were also positively correlated with EDN, IL-1β, IL-10, and IL-6 at four and six weeks." (PMID 35628877, 2022). "Asthma patients had significantly more CD206+ (p = 3.9E-17) and IRF5+ (p = 1.9E-17), and fewer IL10+ macrophages (p = 3.1E-15) than healthy individuals." (PMID 35387061, 2021). "MSC-EVs have been found to increase the production of IL-10 and TGF-ß1 in PBMCs of patients with asthma and reduce inflammation in mice through increased proliferation and immunosuppressive of Tregs35." (PMID 34079033, 2021). "Hyperleptinemia, hyperresistinemia, and lower concentrations of adiponectin, as well as elevated levels of IL-6 and reduced levels of IL-10, were found in patients with T2DM and in those with concomitant T2DM and asthma." (PMID 33520042, 2021). "Our findings provide strong evidence that the down-regulation of miRNA-221-5p increased IL-6, IL-17, IL-21 and IL-22 levels, and reduced IL-10, IL-35 and TGF-β levels in vitro model of asthma." (PMID 34863307, 2021). "For example, as suggested above, both DC-VitD/dex and DC10 secrete IL-10 and thereby induce Th2 cells to differentiate into CD25+Foxp3+ Treg which can fully reverse the asthma phenotype." (PMID 33777019, 2021). "OVA stimulation increased the expressions of IL‐4 and TNF‐α and decreased the expressions of IL‐10 and IFN‐γ in the BALF and plasma, in obese asthma, while metformin reversed these changes." (PMID 33421348, 2021). "In light of that, the up-regulation of IL-10 and TGF-β production by Treg cells should translate into a reduction in the development of immune and inflammatory responses in asthma." (PMID 34071080, 2021). "The levels of inflammatory cytokines IL‐4 and TNF‐α were increased while IL‐10 and IFN‐γ were decreased in obese asthma; metformin reversed these changes." (PMID 33421348, 2021). "In N-ERD vs. asthma comparison, we detected five SNPs in four genes (PPARG, IL10, PTGER2, and OBSCN)." (PMID 31936183, 2020). "The SNPs of IL10 rs1554286 and rs1800872 had a high linkage disequilibrium in the tree comparisons, N-ERD vs. CG and N-ERD vs. asthma had r2 = 0.90, and asthma vs. CG had r2 = 0.93." (PMID 31936183, 2020). "Higher serum levels of TNF-α, IL-13, IL-4, IL-10, hs-CRP and FeNO were determined in asthma patients than in healthy volunteers (P<0.05)." (PMID 33223504, 2020). "Consistent with the results of Th cell subset in mice, the asthma group displayed higher levels of IL-4, IL-17, IL-6, and TGF-β mRNA expression and lower levels of IFN-γ and IL-10 mRNA in the splenocytes than the normal and PBS groups." (PMID 32549755, 2020). "Briefly, the combinations of IL-10 and POSTN, CHI3L1 with IL-10 and POSTN, or CHI3L1 with IL-8 and POSTN are proposed as good or very good sets of biomarkers to differentiate between the two types of asthma." (PMID 31143187, 2019). "Our later works demonstrated experimental evidence supporting possible roles of IL10 and TLR4 in comorbid asthma and hypertension." (PMID 31705029, 2019). "Other studies have also shown that interleukin 10 and 13 have an inverse relationship in patients with COPD and asthma." (PMID 31363402, 2019).
asthma (continued). "Prediction of asthma by cutting off CG site methylation levels of LMO2, GSTM1, and IL10 according to the ROC curve followed by DeLong test." (PMID 31214241, 2019). "In Stage 3 of asthma, local inflammation is induced by Group 3 cytokines such as TGF-βand IL-10 in the bronchus and lung, which leads to tissue repair initiation." (PMID 31284537, 2019). "In a mouse asthma model of asthma, infusing CD4+ CD25+ Tregs can alleviate airway inflammation and airway hyperresponsiveness through increasing the serum level of IL-10." (PMID 30089474, 2018). "When two biomarkers were combined, the combinations of CHI3L1 + POSTN, IL10 + POSTN, IL-8 + PI3, and SERPINB2 + POSTN were good to discriminate severe from moderate–mild asthma, and of smaller importance was the grouping of IL-8 + POSTN." (PMID 29977241, 2018). "Induction of allergic asthma in mice alters the homeostasis of IL-10+ Bregs, and adoptive transfer of CD9+ B cells alone is sufficient to abrogate asthma in an IL-10-dependent manner." (PMID 30622536, 2018). "The asthma group increased the Th2 cytokines and P group increased the Th1 cytokine profile, and A+P+PT+PDT group increased IL-10 cytokine." (PMID 29145431, 2017). "IL-17 and IL-4 were significantly higher in the asthma attack group than in the other three groups, whereas TGF-β, IL-10, and IFN-γ were significantly lower." (PMID 28674387, 2017). "The concentrations of IFN-γ, IL-4, IL-5, IL-10 and IL-17 in BALF were therefore determined, to confirm the establishment of the mouse asthma model at the molecular level." (PMID 28931832, 2017). "For the analyzes of the IL-4, IL-5 IL-10 and IFN-γ cytokines in the BAL supernatant–the cytokines related to the mechanism (Th2) of asthma were evaluated in the BAL supernatant." (PMID 29145431, 2017). "Microarray examination of PBMCs from children with acute exacerbations of asthma revealed a comprehensive list of 52 aaMØ signature genes, including CD163, SOCS1, IL-10, and IL-13R." (PMID 25430775, 2015). "Systemic vitamin D status correlated directly with airway levels of IL-10 and CD4+FoxP3+ T cells in pediatric asthma patients and in healthy controls." (PMID 25852682, 2015). "More recently the group has shown that the regulatory cytokine IL-10 and CD103+CD11b− dendritic cells are necessary to successfully protect against asthma with H. pylori in mice." (PMID 28943607, 2015). "Yet another insight from the asthma research relates to the distinction between CD4+FoxP3−IL-10+ Tr1 cells and CD4+FoxP3+IL-10− Treg cells." (PMID 25852682, 2015). "The current study aimed to investigate the expression of IL-4 and IL-13, as well as IL-6, IL-10 and TNF-α, in the sheep model of asthma following allergen challenge of the airways." (PMID 26362930, 2015). "Whereas IL-10 is important in terminating pro-inflammatory and antiviral immune responses, the presence of this immune regulatory cytokine at the beginning of virus infection could impair the response to viruses and play a role in virus-induced asthma exacerbations." (PMID 25430775, 2015). "Studies in other models (asthma, trauma) demonstrated that Th1 cytokines such as IL-2 and IFN-gamma were increased whereas Th2 cytokines such as IL-4, IL-10 and IL-13 were suppressed." (PMID 24732949, 2014). "A significantly higher percentage of CD4+Foxp3+ cells from asthma patients expressed IFN-γ (P = 0.01), IL-4 (P = 0.004) and CD25 (P = 0.04), whereas the percentage of CD4+IL-10+ cells expressing Foxp3 was significantly decreased in asthmatics (P = 0.03)." (PMID 25132806, 2014). "Differential activation of signaling pathways led to changes in the production of the asthma-relevant cytokines CCL20, CCL2, and IL-10." (PMID 24736642, 2014). "Asthma is believed to have a strong genetic background, and hundreds of genes have been identified to be related with asthma, including GSTM1, IL10, CTLA-4, SPINK5, LTC4S, IL4R, and ADAM33." (PMID 24790987, 2014).